INS (insulin)
Diseases named in the same sentence as INS in open-access papers (continued):
Sharing a sentence is not in itself a finding about the gene and the disease.
diabetes (continued). "In pregnant women with pre-existing diabetes mellitus (DM), physiological changes in insulin sensitivity lead to substantially higher rates of perinatal complications than seen amongst the general population (American Diabetes Association, 2020; Egan, Murphy & Dunne, 2015)." (PMID 33585080, 2021). "The mechanism may be related to protein aggregation, insulin damage, oxidative stress, inflammatory reaction, and the generation of diabetes end products." (PMID 34422242, 2021). "Also, 679 (29%) participants had diabetes, and the study population had a mean fasting glucose of 100 mg/dL, a mean HbA1c percentage of 6, and a fasting insulin of 19 IU/mL." (PMID 34020621, 2021). "With longer duration of diabetes, the clusters might change, and insulin resistant obese cases could be challenging to match to the original SIRD and MOD cluster of corresponding new-onset diabetes." (PMID 34276762, 2021). "Better postoperative outcomes are associated with younger age, shorter duration of diabetes, lack of need of insulin administration, better glycemic control, and certain gut microbiota profiles." (PMID 34501327, 2021). "Interestingly, this study showed that during the short pre-diabetes period, islet volumes were temporarily increased and their scattering properties were five-fold reduced, indicative of insulin hyper-secretion." (PMID 33967961, 2021). "The research aimed to replace injectable insulin as a way to revolutionize diabetes treatment." (PMID 34572086, 2021). "A study indicated that insulin resistance or impaired insulin sensitivity exists in psoriasis patients with normal glucose tolerance, which may further result in the development of diabetes mellitus." (PMID 34803716, 2021). "We also found that there was possible crosstalk between COVID-19 and insulin signaling in diabetes." (PMID 34067609, 2021). "Later on, the IGF2BP2 variant was found to decrease glucose-stimulated insulin secretion in the first but not the second phase of diabetes development." (PMID 33568150, 2021). "Since clinical outcomes are the cardinal motivation to monitor diabetic patients for a longer period of time, we would have expected complications, and cardiovascular morbidity in particular, to be the cornerstone of most diabetes registries, together with HbA1c levels and insulin treatment." (PMID 32770407, 2021). "HbA1c measurements may serve as an alternative biomarker for IGT, and insulin levels could be more systematically measured to detect undiagnosed diabetes, pre-diabetes, or insulin resistance." (PMID 34395368, 2021). "Insulin-secreting stem cells are under investigation for treating diabetes." (PMID 33802091, 2021). "The postprandial insulin levels are more significant following the addition of saturated fat (butter); therefore, in this study, high glucose concentrations were used as a marker for diabetes mellitus." (PMID 34007967, 2021). "However, subgroup analysis revealed a significant, nearly three-year delay in diabetes onset in the group in which first-phase insulin response was lower than the threshold." (PMID 33418839, 2021). "Therefore, the distinction between the roles of insulin and IGF-1 as causes of diabetes and progression of insulin-resistant states is unclear." (PMID 34239560, 2021). "The first commercial insulin pump was introduced in 1983 in an attempt to further optimize blood glucose levels after growing evidence had supported that achievement of near-normal blood glucose levels result in reduction of diabetes-related complications." (PMID 33668749, 2021). "Finally, in the diabetes group, insulin treatment decreased from the first to the last study interval while use of non-insulin anti-diabetic medication increased." (PMID 34863111, 2021).
diabetes (continued). "Given the importance of insulin in the management of diabetes and increasingly available alternatives insulin delivery systems, we believe that the application of the instrument may contribute to implementing care practices based on patients’ preferences." (PMID 34033280, 2021). "Alternatively, patients may have observed improvements in diabetes management in the context of evolving policy changes regarding insulin access and affordability." (PMID 34468753, 2021). "Caffeine increases postprandial hyperglycaemia and reduces insulin sensitivity, and may decrease the effectiveness of diabetes medication (insulin and oral hypoglycaemic agents)." (PMID 34683828, 2021). "Some applications of this work in diabetes are improvements in blood glucose control, recommendations, nutritional advice, individualized treatment, as well as blood glucose level regulation when monitoring night-time insulin values with an insulin pump." (PMID 34450712, 2021). "Moreover, the mixture promotes a decrease in the serum glucose concentration and increases the insulin concentration in treated rats, which are key parameters in the management of diabetes mellitus type 2." (PMID 34500773, 2021). "The Odds ratio was 1.7–2.2 for diabetes treated with diet and 1.7–7.7 for insulin-treated diabetes." (PMID 33803995, 2021). "PPAR-α can improve dysfunction of glucose metabolism in T2DM by increasing insulin sensitivity, reducing hyperglycaemia and hyperinsulinaemia, and alleviate insulin resistance to decrease the incidence of diabetes." (PMID 33981226, 2021). "Compared to well-controlled insulin-treated diabetic patients, patients admitted for ketosis had decreased plasma FC, and further losses in FC were observed in newly diagnosed diabetics with frank acidosis and ketoacidosis." (PMID 34833964, 2021). "Diabetes mellitus (DM) is a heterogeneous group of chronic metabolic conditions of pandemic magnitude, characterized by elevated blood glucose levels, resulting from the inability to produce insulin, resistance to insulin action, or both." (PMID 36994347, 2021). "Treatment compliance: Medical Prescription Knowledge questionnaire, Attitude Scale, Measurement of Adherence to Drug Therapy in Diabetes Mellitus–Oral Antidiabetics (MAT OADS), Measurement of Adherence to Drug Therapy in Diabetes Mellitus–Insulin Therapy (MAT insulin)." (PMID 34397387, 2021). "In fact, it was found that individuals who develop diabetes beyond their teenage years may retain as many as 40% of their insulin positive islets, confirming previous knowledge that the disease process is more fulminant in younger cases." (PMID 33868170, 2021). "In this review we summarize the evidence on the increased presence of mast cells in the pancreas of subjects with type 1 diabetes, which is due to the autoimmune destruction of insulin secreting beta cells, and discuss the differences with type 2 diabetes, the other major form of diabetes." (PMID 34440644, 2021). "It has been reported that IL-1β amplified systemic inflammation and impaired insulin signaling leading to insulin resistant and organ dysfunction in peripheral tissues and macrophages during type 2 diabetes mellitus." (PMID 33986669, 2021). "Diabetes mellitus is a chronic carbohydrate metabolism disease characterized by hyperglycemia, and it is caused by total lack of insulin, insufficient secretion, or synthesis of insulin or peripheral resistance to insulin effect." (PMID 34371645, 2021). "This rise could delay obesity and body weight by increasing thermogenesis and increasing insulin-sensitivity, a key parameter of diabetes." (PMID 34574159, 2021). "Baseline patient characteristics evaluated as potential moderators included age, race, highest level of education attained, employment status, income, health literacy, duration of diabetes, insulin use, baseline HbA1c, diabetes-specific social support, and depression." (PMID 33427667, 2021).
diabetes (continued). "STZ (2-deoxy-2-(3-(methyl-3-nitrosoureido) -D-glucopyranose), a DNA alkylating reagent, is often used to mimic diabetes symptoms for type I, depicted by pancreatic β-cells apoptosis, resulting in hyperglycemia, diminution of insulin gene expression, and reduced synthesis of insulin." (PMID 33440620, 2021). "Notably, individuals with diabetes have been observed to have significant changes related to DNA methylation in the insulin-producing (pancreatic islets) and insulin-targeted tissues (adipose tissue, skeletal muscle, liver)." (PMID 33525677, 2021). "The phenotypes of ABCC8-NNDM were variable and could also present with early hyperinsulinemia followed by reduced insulin secretion, progressing to diabetes later." (PMID 34631896, 2021). "Insulin is used for the treatment of diabetes mellitus, which is characterized by hyperglycemia." (PMID 33466845, 2021). "The following keywords were used in combination: ‘diabetes mellitus’, ‘diabetes’, ‘hyperglycemia’, ‘diabetic ketoacidosis’, ‘prediabetes’, ‘insulin’, ‘oral hypoglycemic agent’, and ‘cancer’, ‘malignancy’, ‘targeted therapy’, ‘immunotherapy’, or ‘cancer therapy’." (PMID 34830886, 2021). "Additionally, GGQLD promotes glucose metabolic disorders, protects pancreatic β cells, and elevates the insulin sensitivity index, thereby exerting an important role in treating diabetes." (PMID 34017258, 2021). "The top 5 most frequently used mHealth apps were identified and rated by the number of consumer reviews, app ratings, and the presence of key diabetes management features, such as dietary blood glucose, A1C, insulin, physical activity, and prescription medication." (PMID 34463627, 2021). "In contrast, none of the 99 replicated urate-associated CpGs were associated with fasting glucose and insulin among individuals without diabetes, who are less likely to be affected by the metabolic syndrome." (PMID 34887389, 2021). "Additionally, animals with controlled diabetes were also used in some studies and those received a subcutaneous sustained-release insulin implant which was aseptically placed in the dorsal side of the animals’ neck." (PMID 34940355, 2021). "Two months after transplantation, one monkey (K) in group 3, which received > 25,000 IEQ/kg, showed indicators of diabetes (blood glucose level, serum C-peptide level, and insulin requirement) and regressed similarly to the monkeys in group 2 after we resected the whole of segment." (PMID 33883656, 2021). "Lastly, we tested if restoring insulin signaling in multidendritic sensory neurons could rescue diabetes-induced mechanical nociceptive hypersensitivity." (PMID 34549177, 2021). "Future studies could investigate whether improved access to diabetes care and technologies, such as insulin pumps, may mitigate the racial disparities in DR prevalence." (PMID 34570208, 2021). "Glucotoxicity regulates fusion pore dynamics by decreasing SNARE complexes, which may be the potential mechanism leading to defective insulin secretion in diabetes." (PMID 33937248, 2021). "Consequently, patients with diabetes, including children, especially if they require insulin, should be increasingly carefully managed and monitored." (PMID 35095504, 2021). "Diabetes is a chronic disease marked by high blood sugar resulting from a decrease in insulin production by pancreatic beta cells, or when the body cannot effectively use the insulin it produces." (PMID 34685875, 2021). "Finally, rising insulin costs remain a concern for people with diabetes, their families and health care providers." (PMID 34824344, 2021). "However, it’s effect on diabetes mellitus and influence on the actions of insulin action remains to be investigated." (PMID 33986669, 2021). "To evaluate whether the blockade of insulin peptide presentation may influence the autoimmune process, we tested the two anti-InsB monoclonal antibodies for their long-term effects in diabetes development." (PMID 33822842, 2021).
diabetes (continued). "The inhibition of MTPN enhances glucose-induced insulin secretion and insulin exocytosis, indicating that miR-375 might be a new therapeutic target for diabetes mellitus and NAFLD." (PMID 33572780, 2021). "With respect to encapsulated carbohydrates in the form of sugar: more distal (ileal) delivery of sugars (glucose) will lead to an increase in GLP-1 release with subsequent insulin release and increase in insulin sensitivity, factors that are beneficial in overweight and type 2 diabetes mellitus." (PMID 34064724, 2021). "Diabetes mellitus (DM) is a group of metabolic disorders characterized by chronic hyperglycemia with abnormalities in the metabolism of carbohydrate, lipid, and protein resulting from defects in insulin secretion, action, or both." (PMID 34125859, 2021). "The high economic and social costs of diabetes and its rising prevalence, especially the Type 2 diabetes where most adults eventually need to get insulin injections, make a strong case for interventions that improve both the quality of outcomes and costs for diabetes patients." (PMID 34663318, 2021). "They found that KGC05P0 could regulate diabetes-related indicators including HbA1c, insulin, glucose tolerance, and fasting glucose level, via downregulating the PI3K/AKT pathway, inhibiting gluconeogenesis." (PMID 33671522, 2021). "Several smartphone apps for diabetes management have been developed, with the aim of help T1Ds to calculate insulin bolus, registered glucose data, track carbohydrate intake, or physical activity, with the possibility of sharing data on glycemic trends with clinicians." (PMID 33755854, 2021). "EIAS mainly occurred in type 2 diabetes mellitus patients using premixed insulin." (PMID 33827670, 2021). "As the insulin signaling pathway controls the transport of glucose in hepatic cells; dysregulation is a key determinant of the glycemic response showed in uncontrolled diabetes." (PMID 34667196, 2021). "In addition, high-protein diets (≥25% energy intake from protein) have been shown to decrease body weight and fat mass and improve insulin sensitivity and blood pressure in individuals with obesity and patients with diabetes." (PMID 34485407, 2021). "Diabetes is a chronic metabolic disease characterized by an increase in blood sugar levels due to the body’s resistance to insulin or its inability to produce enough insulin, which can lead to serious complications over time." (PMID 34823419, 2021). "Regardless of the precise mechanism, the fact that this druggable target can be specifically chemically inhibited deserves further attention as a means to enhance insulin production for the treatment of diabetes, and for possible use in other, similar diseases." (PMID 34645803, 2021). "Next we tested if the effect of the insulin signaling measure was differential by diabetes status." (PMID 33858515, 2021). "Future studies can examine the factors that affect the glycation of proteins of HDL in patients with T1D and whether metformin or other diabetes drugs such as insulin could restore the CEC of glycated forms of HDL in patients with T1D." (PMID 34277985, 2021). "Previous reports have shown that CoQ10 could improve glycemic control in diabetes mellitus (DM) patients by improving insulin secretion and reducing oxidative stress." (PMID 34574891, 2021). "Also in Pima Indians, increased clamp lipid oxidation predicted diabetes prospectively, after adjustment for relevant confounders including glucose disposal, acute insulin response, age, sex, and body fat." (PMID 33616083, 2021). "In addition, P. freudenreichii MJ2 effectively alleviates diabetes by reducing blood glucose and fasting blood insulin." (PMID 33510408, 2021). "Insulin has played a pivotal role far beyond its application in diabetes therapy." (PMID 35602193, 2021). "However, technological innovations such as continuous glucose monitoring and automatic insulin delivery have changed terms and expressions in diabetes care." (PMID 36994332, 2021).
diabetes (continued). "ROS can exert numerous detrimental effects that induce and aggravate diabetes, including diminishing glucose transport channels, reducing insulin secretion, protein fragmentation and oxidation, DNA damage, free fatty acid generation, and increased vascular permeability." (PMID 34012421, 2021). "As insulin therapy is usually reserved for advanced type 2 or type 1 diabetes, this may reflect patients with increased diabetes severity." (PMID 34293038, 2021). "This builds on the WHO prequalification initiatives, and is seen as critical given the envisaged increase in prevalence rates and costs of diabetes, and the need to appropriately manage patients requiring insulin to reduce hypoglycaemia and improve adherence rates to reduce future complications." (PMID 34249838, 2021). "Wearing a CGM facilitates greater awareness of BG patterns, wearing a pump facilitates more frequent and timely administration of insulin, and having a computer or mobile phone with internet access facilitates seamless data downloads from diabetes devices to review and adjust insulin." (PMID 34709387, 2021). "According to statistics from the National Health Insurance (NHI) database in Taiwan, the use of insulin regimens increased annually until 2014, with 4.67% of people with diabetes using insulin injections alone, and 8.01% using concomitant oral agents and insulin." (PMID 34574483, 2021). "Besides thyroid dysfunction, in two patients (2.86%) the onset of type 1 diabetes mellitus was reported and insulin treatment was started." (PMID 34036513, 2021). "It’s of great significance to develop insulin-loaded dissolving microneedles (MNs) which are fabricated with various methods and materials for transdermal delivery of insulin to effectively and efficiently treat diabetes." (PMID 34630098, 2021). "People with diabetes may benefit from IN insulin if a long-acting version is administered instead of a short-acting form." (PMID 34540446, 2021). "The March 2020 peak and April–May drop was evident in both insulin and non-insulin diabetes medicines." (PMID 34209616, 2021). "Insulin utilisation increased to 3.19 billion DDDs in the public health system in South Africa in 2019, an increase of 11.1% compared with 2018, reflecting increased diabetes prevalence rates." (PMID 34249838, 2021). "The insulin sensitivity index is closely related to diabetes." (PMID 33663083, 2021). "Diabetes is a group of metabolic diseases characterized by chronic hyperglycemia caused by a variety of reasons, of which 90% are type 2 diabetes mellitus (T2DM), and the main pathophysiological mechanisms are insulin resistance and relatively insufficient insulin secretion." (PMID 34858327, 2021). "Most diabetes cases are type 2 diabetes, which is a condition determined by a combination of reduced insulin action in the insulin target tissues, i.e., insulin resistance, and an insufficient compensation for this insulin resistance due to an impaired insulin secretion." (PMID 34591793, 2021). "Alterations of global DNA methylation profile may be at the basis of key dynamic epigenetic states that impair the expression of diabetes-related genes, finally resulting in the manifestation of pro-inflammatory, insulin-resistant phenotypes." (PMID 34001206, 2021). "Further research should focus on the effects of isomaltulose ingestion on concentrations of glucose, insulin and GIP during exercise in clinical populations, such as diabetes or obesity, as there is often a higher hypoglaemic risk during exercise following a meal." (PMID 34001166, 2021). "Technology can simplify the management of diabetes: as an example, smart insulin pens with memory functions could record the insulin doses administered and transfer data via Bluetooth to dedicated apps." (PMID 33755854, 2021). "In diabetes, protein tyrosine phosphatase is known to act as a negative regulator of insulin signaling, and expression of PTPRC is associated with residual β-cell function in type 1 diabetes." (PMID 35145474, 2021).